STAT3 (signal transducer and activator of transcription 3)
Diseases named in the same sentence as STAT3 in open-access papers (continued):
Sharing a sentence is not in itself a finding about the gene and the disease.
tumor (continued). "IL-6, activating the JAK/STAT3 pathway, stimulates inflammatory processes in the tumor microenvironment, which paradoxically support tumor development, promote angiogenesis, and support the adaptation of tumor cells to therapy, including chemotherapy." (PMID 40362280, 2025). "In vivo experiments using a mouse model showed that RES treatment significantly reduced lung tumor size and weight, and downregulated the activation of STAT3 in tumor cells." (PMID 40860906, 2025). "Multiple studies have demonstrated that IL-6 induces VEGF expression via the JAK/STAT3 signaling pathway, thereby contributing to angiogenesis and tumor invasion." (PMID 41010841, 2025). "Pro-inflammatory cytokines, such as IL-6, TNFα, IL-1β, and IFNγ, enhance the activation of key signaling pathways like NF-κB and STAT3, which drive tumor progression." (PMID 40943532, 2025). "Ectopic expression of integrin β3 in STAT3KO cells partially restored tumor initiation, bypassing the requirement for STAT3." (PMID 40701148, 2025). "Overexpression of miR-217 reduces IL-6 levels, which in turn inhibits the JAK2/STAT3 pathway, decreasing M2 macrophage markers and promoting an immune environment less conducive to tumor progression." (PMID 40330466, 2025). "miR-637 is able to modulating the Jak/STAT3, Wnt/β-catenin, and PI3K/Akt signaling pathways; it is downregulated in cancer and is associated to larger tumors and later tumor node metastasis staging in cancer patients." (PMID 40061896, 2025). "Cytotoxic T lymphocyte subset 9 (Tc9) reduces lipid peroxidation and declines ferroptosis stress to durably kill tumor cell through STAT3-mediated FAO upregulation." (PMID 40290117, 2025). "Conditioned medium from C26 tumor cells (which secrete high LIF) causes severe atrophy of cultured myotubes and robust STAT3 activation." (PMID 40869331, 2025). "Building upon the understanding that leptin facilitates the migration and invasion of cancer cells through the JAK2/STAT3 signaling pathway, we investigated the influence of leptin within OB EVs on these critical stages of tumor metastasis." (PMID 40485730, 2025). "Curcumin, in particular, regulates the JAK/STAT3 pathway, inhibits tumor growth, and improves immunotherapy efficacy." (PMID 40406101, 2025). "In tumor tissue collected after 7 days of treatment, the interaction of STAT3 with LSD1 increased in BRAFi + EGFRi relative to vehicle tumors but this increase was attenuated with the addition of SP-2577 treatment." (PMID 40264166, 2025). "Tumor-derived CXCL1 further activates STAT3/NF-κB pathway in adipocytes to promote IL6 expression and secretion in adipocytes, and finally forms a cascade of interaction." (PMID 40841364, 2025). "Aging immune cells also promote tumor metabolic reprogramming via cytokines and secreted factors: Senescent immune or stromal cells secrete pro-inflammatory SASP factors (e.g., IL-6, IL-8, TNF-α, CXCL1), activating STAT3 and NF-κB pathways in tumor cells." (PMID 40881346, 2025). "Studies have confirmed that the dysregulated activation of STAT3 in multiple tumors plays a critical role in different aspects of oncogenesis and tumor-immune evasion." (PMID 40529368, 2025). "NF-κB and STAT3 act as oncogenes, enhancing the metastasis potential of tumor cells and promoting tumor development and progression." (PMID 40786506, 2025). "The results of WB show that the phosphorylation levels of JAK2 and STAT3 in the subcutaneous tumor tissues were significantly downregulated." (PMID 39852843, 2025). "Similar phenotypical changes in STAT3-deficient TANs and TDLN neutrophils were also observed in the B16-F10 tumor model." (PMID 40885734, 2025). "Activated STAT3 within tumor cells has been shown to promote tumor development through transcriptional activation of gene targets that improve cancer survival, stemness, proliferation, and invasiveness." (PMID 40356899, 2025).
tumor (continued). "At the nexus of numerous oncogenic signaling cascades, STAT3 assumes a pivotal role in modulating the anti-tumor immune response." (PMID 40143965, 2025). "STAT3 can be activated in a variety of human tumors, and STAT3 overexpression has been observed in a variety of patient-derived tumor tissue samples." (PMID 40143965, 2025). "An important mechanistic insight from this study is that APE directly targets the STAT3 signaling pathway, which plays a crucial role in promoting tumor progression, survival, and cisplatin resistance." (PMID 40278288, 2025). "Since phosphorylation at serine 727 of STAT3 is characteristic of more undifferentiated tumor forms, the interplay between the latter and the AhR-NOX1-ROS axis plays a significant role even in the later stages of chemical carcinogenesis." (PMID 40141386, 2025). "STAT3 is a key oncogenic transcription factor that is constitutively activated in tumor cells and immune TMEs, serving as a key signaling hub integrating multiple oncogenic signaling pathways." (PMID 40364836, 2025). "Due to its central involvement in tumor initiation and advancement, the IL-6/STAT3 pathway is increasingly recognized as a promising focus for small-molecule drug development." (PMID 40723906, 2025). "Specifically, CAF-derived WNT2 disrupts the JAK2/STAT3 signaling pathway, essential for maintaining DC differentiation, leading to diminished anti-tumor immunity." (PMID 40453074, 2025). "Many human tumours have hyperactive signal transducer and activator of transcription 3 (STAT3, positioning it as a prime target for natural compounds with anticancer properties." (PMID 40061959, 2025). "The lowest rate of positive STAT3 tumor samples was found in the iCCA group and in the GBC subgroup (50%), while the highest rate was found in the dCCA group (71%)." (PMID 40426911, 2025). "WP1066 effectively inhibits the expression of STAT3 and reduces PD‐L1 expression, thereby significantly inhibiting tumor immune escape and enhancing antitumor efficacy in a synergistic manner." (PMID 40364727, 2025). "Blocking IL-8 or inhibiting STAT3 activation disrupted these effects, indicating that the IL-8/STAT3 axis plays a crucial role in the interaction between OCSLCs and macrophages, driving tumor progression and cancer cell stemness." (PMID 40330466, 2025). "Accumulating evidence has illustrated that the IL-6/IL-6R/STAT3 pathway plays a pivotal role in tumor occurrence and progression; however, the detailed mechanism has not yet been identified." (PMID 40779629, 2025). "To determine the role of IL-10-STAT1/STAT3 axis in ER stress induced by CAP treatment in tumor cells, we treated the separately cultured Calu-1 cells with exogenous IL-10 (20 μg/mL) to mimic the possible release of IL-10 from CAP-treated macrophage." (PMID 41145470, 2025). "In this context, CHI3L1 acts as a downstream effector of STAT3 and promotes tumor progression by enhancing the production of inflammatory cytokines." (PMID 40643503, 2025). "Derivatives like FLLL32 degrade STAT3, suppressing tumor angiogenesis (VEGF) and metastasis (MMP-2/9) in preclinical osteosarcoma models." (PMID 40918117, 2025). "Specifically, the activation of the PAF/PAFR signaling pathway stimulated the STAT3 pathway, which is primarily responsible for regulating tumor growth." (PMID 40033370, 2025). "Collectively, these data show that hypoxia-induced sustained EGFR activation endows tumor cells with drug resistance through STAT3-mediated induction of autophagy." (PMID 40940319, 2025). "Studies have shown that GABA can upregulate the expression of PD-L1 on the surface of tumor cells by activating the STAT3 signaling pathway, thereby suppressing anti-tumor immune responses." (PMID 40837580, 2025). "PYK2 in tumor exosomes can also trigger STAT3 activation in macrophages by activating the RhoA pathway in OS cells." (PMID 40028322, 2025).
tumor (continued). "EGCG, the primary catechin in green tea, inhibits tumor-promoting pathways by blocking NF-κB and STAT3 activation, thus reducing the transcription of IL-6, MMP-9, and CD44." (PMID 40869364, 2025). "IL-6 maintains JAK/STAT3 signaling, amplifying its own expression and promoting resistance to oxidative stress, tumor invasion, and chemoresistance." (PMID 41383608, 2025). "IgG4 promotes colon cancer progression by inducing tolerogenic M2-like macrophages via FcγRI and PI3K/AKT/STAT3 signaling, leading to an immunosuppressive tumor microenvironment." (PMID 41357192, 2025). "In conclusion, our study revealed that STA-induced inhibition of the JAK2/STAT3 pathway in macrophages can suppress TAMs M2 polarization and further inhibiting tumor cell migration and angiogenesis." (PMID 39974738, 2025). "Once it is expressed, STAT3 transmits information to tumor cells and acts on its target genes to regulate tumor cell proliferation, differentiation and metastasis." (PMID 39907159, 2025). "Combining FAK inhibitors with Janus kinase/STAT3 inhibition has yielded significant tumor growth inhibition and increased survival across multiple PDAC mouse models, highlighting the potential of dual stromal and tumor-targeting therapies." (PMID 39976799, 2025). "NcRNAs also play a role in inflammatory signaling, particularly through NF-κB and STAT3 pathways, linking oxidative stress to chronic inflammation and tumor progression." (PMID 40563255, 2025). "STAT3, a pivotal transcription factor involved in tumor cell survival and proliferation, also mediates tumor-promoting inflammation." (PMID 41200178, 2025). "The exposure to IL-6 leads to the chronic induction of STAT3 phosphorylation, which promotes further growth and invasion of these tumor cells." (PMID 40940764, 2025). "Overactivation of STAT3 contributes to resistance against apoptosis and enhances immune suppression within the tumor microenvironment." (PMID 40607416, 2025). "In our hands, we were able to pharmacologically target STAT3 after initial tumor formation but saw decreased tumor growth." (PMID 40356899, 2025). "Knockdown of exosomal proteasome subunit alpha 5 (PSMA5) derived from HCC cells impeded M2 macrophage polarization via abrogating JAK2/STAT3 signaling pathway, leading to inhibited tumor cell proliferation, invasion, and migration." (PMID 40264760, 2025). "The ethanol extracts of A. cinnamonea inhibited tumor growth and induced apoptosis via inhibiting the STAT3 signaling pathway." (PMID 40142097, 2025). "Unaltered CCL5 expression indicates that tumor cells did not activate astrocytes’ tumor-suppressive functions but instead promoted tumor-supportive properties, as evidenced by significant upregulation of STAT3 signaling following tumor cell exposure." (PMID 40149331, 2025). "Since STAT3 activation is sustained by IL-6 signaling, CCNB1 likely contributes to a positive feedback loop between IL-6 and JAK-STAT3, further reinforcing tumor immune evasion." (PMID 40430484, 2025). "In other words, quercetin inhibits JAK2/STAT3/PD‐L1, thereby preventing the immune escape of tumor cells." (PMID 41195524, 2025). "Specifically, the 200 nm iRGD‐SPNPs accumulated preferentially in immunosuppressive TAMs and tumor endothelium, reversed STAT3 signaling, and thereby unleashed T cell–mediated antitumor immunity." (PMID 41583439, 2025). "As a receptor present on the surface of tumor cells, csGRP78 can interact with various signaling molecules, leading to the initiation of downstream cascades involving STAT3, RAS/MAPK and PI3K/AKT/mTOR." (PMID 39629920, 2025). "Consistent with previous results, neutrophil-specific STAT3 knockdown impaired tumor growth and enhanced cytotoxic T cell activity in the tumors and tumor-draining lymph nodes of treated mice." (PMID 40885734, 2025). "IL-6 promotes tumor growth, immune modulation, and inflammation by activating STAT3 pathways, which maintain constitutive nuclear factor-κB (NF-κB) signaling." (PMID 40227644, 2025).
tumor (continued). "IL-6 acts on tumor cells to induce STAT3 target genes that promote proliferation and survival, creating a feedforward autocrine loop." (PMID 40868199, 2025). "In xenograft models, such as B16F10 melanoma, MDA-MB-231 breast cancer, or PC-3 prostate carcinoma, garcinol inhibits tumor growth by downregulating NF-κB, STAT3, and PI3K/AKT signaling while inducing apoptosis and reducing the cancer stem cell phenotype." (PMID 41303402, 2025). "As a nexus for multiple oncogenic signaling pathways, STAT3 assumes a pivotal role in orchestrating the anti-tumor immune response." (PMID 40641526, 2025). "Specifically, SIRT7 acts as a desuccinylase targeting MVP at K437, which in turn activates JAK2/STAT3 signaling to drive tumor cell proliferation, migration, and invasion." (PMID 40586636, 2025). "PTL also exhibits promising anti-tumor properties, particularly through its interactions with critical signaling pathways such as NF-kB and STAT3, which regulate cell survival and apoptosis." (PMID 40958860, 2025). "The treatment led to a 50–65% reduction in STAT3 expression in vitro and significantly inhibited tumor growth in vivo, ultimately prolonging median survival compared to untreated controls." (PMID 40725021, 2025). "These nanoparticles regulate the STING/STAT3 signaling axis and effectively inhibit tumor proliferation and survival." (PMID 40420798, 2025). "In a model of bacterial‐driven colitis‐associated cancer, the production of IL‐22 is crucial for sustaining CRC, activating the STAT3 signalling pathway in epithelial cells, thereby enhancing proliferation and supporting tumour growth." (PMID 40899118, 2025). "For example, IL-6 activates the JAK/STAT3 axis to promote tumor growth and immune evasion, while TNF-α and IL-8 enhance tumor invasion via NF-κB and MAPK signaling." (PMID 41502517, 2025). "Its mechanism is to inhibit NETs formation, reduce neutrophil recruitment and MPO expression in the liver and MDSCs in the lung and tumor by blocking P-selectin, inhibiting NF-κB and STAT3 signalling pathways." (PMID 41019086, 2025). "On the other hand, tumor-growth-related pathways like the STAT3 and PI3K/AKT pathways were less active in the 4F-Dox (+)7d group and even more significantly downregulated in 4F-Dox (+)7d-Pal (+)3d cells." (PMID 40715046, 2025). "Interleukin-6 (IL-6) and IL-8 promote tumor angiogenesis and metastasis by activating the STAT3 and NF-κB pathways." (PMID 40823082, 2025). "Statistically, COX2 and p-STAT1 expression was significantly lower in HCC tumor tissues than in adjacent normal liver tissues, and nuclear pTyr-STAT3 expression was significantly higher in HCC tumor tissues than in adjacent normal liver tissues." (PMID 39826687, 2025). "MDSC expansion can be promoted by cancer cell-derived EVs carrying PD-L1 via IL-6/STAT3 signaling, enhancing immune suppression and tumor progression in gastric cancer." (PMID 40574844, 2025). "Tumor cell-derived RNase1 induces the polarization of TAMs from the M1 to the M2 phenotype by activating ALK/STAT3 signaling and attenuating STAT1 phosphorylation." (PMID 40607254, 2025). "Noteworthily, activated p38 MAPK/STAT3 signaling is required for inducing autophagy 46, which enhances the proliferation and survival of tumor cells." (PMID 41281755, 2025). "Various DDSs, including NPs, liposomes, micelles, dendrimers, and hydrogels, have been explored to increase the accumulation of STAT3 inhibitors at tumor sites." (PMID 40166646, 2025). "STAT3 also plays a role in metabolic reprogramming, facilitating glycolysis and oxidative phosphorylation, which are crucial for tumor cell survival and proliferation (Poli and Camporeale 2015; Tošić and Frank 2021)." (PMID 40860906, 2025). "The tumor-promoting effect of EIF2B4 was found to be STAT3-dependent, as STAT3 knockout completely abolished EIF2B4-driven phenotypes." (PMID 41144132, 2025).
tumor (continued). "TAMs were previously shown to activate the JAK2/STAT3 pathway through IL-6, inhibit tumor suppressor miRNAs like R-506-3p and its target FoxQ1, secrete CCL22, and activate the PI3K/AKT pathway." (PMID 40607405, 2025). "This multi-directional Stat3 signaling exemplifies how a single pathway integrates signals across diverse cellular compartments to drive tumor-promoting effects." (PMID 41584838, 2025). "In tumor associated fibroblasts, a feedforward loop involving mesenchymal pathways JAK1/STAT3 and ROCK-mediated contractility has been identified, which leads to ECM remodeling." (PMID 41199904, 2025). "Aberrant STAT3 expression via IL‐6 proliferation and lncRNA Casc2 lost have been shown to have carcinogenic effects on various tumours, including CRC." (PMID 40118773, 2025). "PSCs release IL-6 to cross-talk with tumor cells, activating STAT3 signaling and promoting invasive phenotypes." (PMID 40948749, 2025). "The signal transducer and activator of transcription 3 (STAT-3) is constitutively activated in a large number of solid tumors and hematologic malignancies, which propels the tumor cells’ malignant activity." (PMID 40227645, 2025). "JAK2/STAT3 is a classical regulatory pathway for the proliferation and apoptosis of malignant tumor cells." (PMID 41200213, 2025). "At the same time, CAFs in the tumor microenvironment activate STAT3 signaling by secreting IL-6, promoting the maintenance of stemness and immune escape of resistant clones, driving clonal evolution." (PMID 41293424, 2025). "Western blot analysis further confirmed that APE reduces both STAT3 phosphorylation at Tyr705 and total STAT3 protein levels, leading to the suppression of downstream targets such as c-Myc, a key oncogene involved in tumor growth." (PMID 40278288, 2025). "This polarization is driven by tumor cell-secreted factors and chemokines, reinforced through STAT3 and NF-κB signaling pathways, establishing an immunosuppressive milieu that promotes tumor growth." (PMID 41479912, 2025). "MSLs downregulate the expression of STAT3 in the tumor microenvironment, promoting cancer cell apoptosis and enhancing the anti-tumor immune response." (PMID 40868764, 2025). "Immunohistochemical analysis of the mouse xenograft tumor model further confirmed significant JAK/STAT3 pathway activation in CXCL7-OE group." (PMID 39915476, 2025). "Inhibits NF-κB and STAT3, induces apoptosis via the mitochondrial pathway, reduces tumor cell invasion and migration, and enhances chemosensitivity to gemcitabine." (PMID 40918117, 2025). "IL7R signaling contributes to immune evasion by promoting M0 macrophage polarization toward an immunosuppressive M2 phenotype, suppressing cytotoxic T—cell activity, and enhancing tumor cell survival through JAK—STAT3 pathway activation." (PMID 40165301, 2025). "The combination of STAT3 inhibitors has the potential to enhance tumor suppression and counteract resistance mechanisms through a synergistic approach." (PMID 40166646, 2025). "These sEVs are internalized by macrophages, where their miRNAs suppress SOCS4/5 expression and enhance STAT3 phosphorylation, inducing TAMs to polarize towards the M2 subtype and promoting tumor proliferation and migration." (PMID 40008006, 2025). "Other reports consistently show that STAT3 activation suppresses interferon (IFN)-driven cytokine signaling and is frequently implicated in tumor-mediated immune evasion." (PMID 41463176, 2025). "We demonstrated that the intratumoral injection of CpG-Stat3ASO into WT mice strongly impaired tumor growth and promoted the expansion of cytotoxic T cells, which was comparable to the results obtained in neutrophil-Stat3 knockout mice." (PMID 40885734, 2025). "Glutamate released by tumor cells can promote the phosphorylation of STAT3 in neutrophils, transitioning them from a tumor-killing phenotype to an immunosuppressive phenotype, a process believed to represent a shift from N1 to N2." (PMID 40342932, 2025).